CRP (C-reactive protein)
Diseases named in the same sentence as CRP in open-access papers (continued):
Sharing a sentence is not in itself a finding about the gene and the disease.
Obesity (continued). "Oxidative stress and lipolysis due to obesity-associated inflammation, which is indicated by elevated levels of TBARS, NEFA, and SAA in basal and postoperative LDL, as well as increased plasma CRP one year postoperatively, contribute to these proatherogenic LDL alterations." (PMID 37777014, 2023). "However, a close relationship between leptin and CRP highlights that maybe the former is functionally involved in inflammation and atherothrombosis, apart from the pathophysiology of obesity." (PMID 37873776, 2023). "Likewise, we found that the obesity-related DP could play a role in related inflammation pathways because C-reactive protein, one of the proxy indicators of inflammation, was the potential mediator in this study." (PMID 37424008, 2023). "Additionally, obesity may result in the increased secretion of pro-inflammatory cytokines, including TNF-α, IL-6 and CRP, causing chronic inflammation, and the impaired quality and development of embryos." (PMID 36742394, 2023). "Firstly, CRP elevation in rural Ghana is more likely because of infectious causes rather than obesity-related inflammation, as in this setting, infectious diseases, such as malaria and helminthic infections, prevail, and risk factors for CVD are relatively less common." (PMID 34478414, 2022). "Obesity causes a state of a chronic low-grade systemic inflammation, with elevated levels of certain circulating proinflammatory adipokines, such as TNF-α, IL−6, leptin, plasminogen activator inhibitor-1 (PAI-1), angiotensinogen, and CRP, as well as lower levels of adiponectin." (PMID 36555411, 2022). "Nowadays, overweight and obesity have been viewed as chronic inflammatory conditions that might trigger inflammation and oxidative stress, resulting in increased levels of certain inflammatory cytokines and C-reactive protein." (PMID 36233388, 2022). "Finally, overweight, obesity, snoring, obstructive sleep apnoea syndrome, hypertension, type 2 diabetes, CRP levels ≥ 1 and <3 mg/L, CRP levels ≥ 3 mg/L, and alexithymia were more frequent in major depressed individuals with dyslipidaemia than in major depressed individuals without dyslipidaemia." (PMID 35755481, 2022). "The influence of stress on the increase in BMI and other obesity markers and their subsequent influence on CRP levels suggest that body adiposity may operate as a mediating mechanism linking stressful life experiences to CRP." (PMID 35629167, 2022). "Maternal prepregnancy obesity or excessive weight gain during pregnancy would lead to chronic systemic inflammation and placental inflammatory response, causing increased concentrations of pro-inflammatory cytokines such as IL-6, IL-8, tumor necrosis factor-α (TNF-α) and C-reactive protein (CRP)." (PMID 36364875, 2022). "Therefore, in the case of an infected patient with obesity, there may be a summation of both conditions for elevated CRP levels." (PMID 35837843, 2022). "Furthermore, circulating levels might also reflect obesity-related low-grade inflammation, which is characterized by increased levels of inflammation markers such as C-reactive protein (CRP) and adipokines, such as leptin, secreted from the adipose tissue." (PMID 36407523, 2022). "In obesity, visceral adipose tissue downregulates the expression of anti-inflammatory adipocytokines, such as adiponectin, that protects the vascular endothelium and upregulates the expression of several proinflammatory mediators, including C-reactive protein (CRP) and interleukin-6 (IL-6)." (PMID 36258233, 2022). "It is well known that obesity leads to an elevated inflammatory response and that excess adipose tissue increases the secretion of pro-inflammatory cytokines, markers of inflammation, including interleukin 6, interleukin 8, tumor necrosis factor, and C-reactive protein." (PMID 36388204, 2022).
Obesity (continued). "As IL-6 and CRP reflect the degree of metabolic inflammation in obesity, our data might suggest that Parasutterella mediates its negative effects on host glucose metabolism – at least in the periphery – via direct metabolic effects rather by influencing the innate immune system." (PMID 35435797, 2022). "In addition, studies demonstrated that human adipocytes could produce CRP under the stimulation of several proinflammatory cytokines, suggesting a link between obesity and its comorbidities, including IR." (PMID 35620114, 2022). "Furthermore, pre-pregnancy obesity and several lifestyle factors, including a diet rich in meat and processed foods, correlate directly with high concentrations of circulating inflammatory biomarkers, such as CRP and IL-6." (PMID 35270396, 2022). "In this regard, in a pilot study of 260 women with obesity, we recently reported changes in PhA during the active phase of the VLCKD that occurred very early and independently of weight loss and were negatively associated with high-sensitive C-reactive protein levels." (PMID 36670880, 2022). "This study showed that four factors (male sex, obesity, patent false lumen, and D-dimer level ≥ 14.5 μg/mL) that can be evaluated at the time of admission could be used to predict hypoxemia, similar to peak CRP level, on the basis of the ROC curves." (PMID 34862435, 2021). "The characteristic profile of soluble factors in obesity and aging, such as decreased adiponectin, elevated levels of C-reactive protein (CRP), leptin, tumor necrosis factor-α (TNF-α), and interleukin 6 (IL-6), could lead to progressive loss of muscle mass and an increase in fat mass." (PMID 34676021, 2021). "Moreover, 12 weeks of intervention (weight-loss program + exercise) in patients with asthma and obesity were not sufficient to improve CRP levels." (PMID 34836393, 2021). "Available studies, mostly conducted in the second trimester, report elevated CRP with elevated or unchanged hepcidin, sTfR and IL-6, suggesting that an inflammatory profile is present in pregnant women with obesity and thus could be playing a role in ID/IDA of overweight/obese pregnancy." (PMID 34067098, 2021). "From the population-based Study of Health in Pomerania, 3366 participants, without (2366) and with (1000) obesity, were studied for the association of periodontitis, measured as probing depth (PD) and plaque together with body mass index (BMI) on C-reactive protein (CRP)." (PMID 32827080, 2021). "The tumor-killing effector cells (CD8+ T) were suppressed and the immunosuppressor cells (MDSCs/M2) were over-activated to drive their recruitment and suppressive capacity, which could be mediated by obesity-related molecular markers, such as IL-6, CRP, leptin, IL-1β." (PMID 34350120, 2021). "firstly proposed that obesity was a correlative factor, as more increased risk of RT-related pain appeared in obese patients (pre-RT CRP ≥ 10 mg/L) than those non-obese patients (pre-RT CRP < 10 mg/L)." (PMID 34350120, 2021). "Furthermore, since adipocytes release proinflammatory markers (TNF-a, IL-6, and CRP), obesity may dysregulate the inflammatory markers and potentiate the inflammatory response, which could lead to higher pain sensitivity." (PMID 34257764, 2021). "Moreover, muscle strength counteracts obesity-driven CRP increase." (PMID 32827080, 2021). "A mutual relationship might exist among obesity, CRP, and periodontitis." (PMID 32827080, 2021). "Besides, alanine transaminase (ALT) and C-reactive protein (CRP) were higher in obesity group." (PMID 34963447, 2021). "Obesity has been shown to be associated with the production of dysregulated cytokines and augment the synthesis of acute-phase reactants, such as IL-6, IL-8, TNF-α, C-reactive protein (CRP), and monocyte chemotactic protein-1 (MCP-1) in patients with obesity and various animal models of obesity." (PMID 34220807, 2021).
Obesity (continued). "The current study could be extended by including the measurement of obesity-related plasma and tissue biomarkers such as adiponectin and C-reactive protein, inflammatory mediators such as TNF and functional changes in the colon such as short-chain fatty acid production." (PMID 34064139, 2021). "Additionally, levels of CCL2 and CRP decreased with gestational age in mothers with obesity." (PMID 34195568, 2021). "Metabolic disorders such as obesity and DM (diabesity) are known to be associated with low-grade chronic inflammation (metaflammation) and endothelial dysfunction, and were identified as risk factors for HF and HFH, also in post-infarct patients with elevated CRP." (PMID 33804661, 2021). "Likewise, previous RCTs performed in samples of participants with overweight or obesity and increased cardiovascular risk have shown no significant alterations in CRP levels by increased FV intake." (PMID 34836009, 2021). "However, because obesity is characterized by chronic systemic inflammation, it is known to be a condition associated with increased production of pro-inflammatory cytokines, such as CRP (C-reactive protein) and interleukin-6 (IL-6)." (PMID 34835945, 2021). "These factors may cause obesity through the “CRP—chronic non-communicable inflammation signal—innate immune system” pathway." (PMID 32154244, 2020). "These associations were independent of known risk factors for NAFLD such as obesity (defined according to BMI and WC in the present study), MetS and its components, age, smoking, sedentary behaviour, physical inactivity, elevated CRP, elevated SUA, and high salt intake." (PMID 32518245, 2020). "In addition, (after adjustments for potential confounders) a two-way ANCOVA showed that high levels of CRF attenuated the associations of C-reactive protein levels in metabolic healthy non-overweight and in adolescents with obesity." (PMID 32443557, 2020). "In obesity, low vitamin C status correlates with inflammatory reactions and vascular dysfunction, and a dose of 1 g/day vitamin C treatment for 8 weeks could reduce CRP and IL-6 levels in both hypertensive and diabetic obese patients." (PMID 33195370, 2020). "Similarly, youth with severe obesity had a higher prevalence of co-morbidities including, asthma, OSA, depression, presence of multiple cardiometabolic risk factors, low HDL-C, elevated HOMA-IR and elevated hs-CRP." (PMID 32522176, 2020). "Notably, both IL-6 and CRP are elevated with obesity and modulate MDSC dynamics." (PMID 33123173, 2020). "Also, some of the regression models will contain interaction terms to test whether education moderates the effect of C-reactive protein on obesity." (PMID 31728932, 2020). "As well, very recent studies suggest that CRP is not only capable of binding to leptin but may compete with it for binding to the leptin receptor, which may lead to leptin resistance and, as a result, obesity." (PMID 32027700, 2020). "This regression was adjusted for sex, BMI, HOMA-IR, CRP and hypertension (yes/no), which are related to the metabolic alterations most frequently associated with the presence and development of obesity: insulin resistance (HOMA-IR), inflammation (CRP) and hypertension." (PMID 33147793, 2020). "CRP may be a new therapeutic target for obesity and its complications." (PMID 32154244, 2020). "Hence, it is tempting to speculate that the decreased expression of TUG1 in adipose tissue may be partly related to the inflammatory milieu in obesity which in turn exacerbates inflammation in obesity, reflected by high levels of hs-CRP." (PMID 32368256, 2020). "Additionally, obesity coexisting with the remaining components of the metabolic syndrome may increase CRP concentration independently of disease activity, which is probably the reason for the lack of any linear correlations between I-FABP and CRP in our study." (PMID 31336842, 2019).
Obesity (continued). "RBP4 is thought be related to obesity, insulin resistance, type-2 diabetes, and metabolic syndrome and is suggested to be an early indicator of the development of insulin resistance and metabolic syndrome, and that this adiponectin is more sensitive to insulin than leptin, IL-6, and CRP." (PMID 30761880, 2019). "Therefore, it is not surprising that inflammation (CRP) and obesity (BMI) were related herein; however, we do not consider that this association trivially accounts for increased CRP in treatment-resistant depression." (PMID 29764522, 2019). "In addition, the Adpn/Lep ratio negatively correlates with the markers of inflammation SAA and CRP, suggesting that this marker may reflect the systemic inflammation in the context of obesity." (PMID 31484347, 2019). "As CRP levels are clearly correlated with measures of obesity and there is a genetic correlation between physical activity and LDL-C, it is possible that inclusion of covariates of adiposity, lipids and blood pressure could result in "over-adjustment", reducing power to detect linkage." (PMID 31622379, 2019). "In addition, obesity presented a significant relationship with high CRP serum levels." (PMID 30728031, 2019). "Research suggests that obesity may be characterized by a low-grade chronic inflammatory state as reflected by elevated levels in many inflammatory markers in the serum, such as IL-6 and C-reactive protein (CRP)." (PMID 29623147, 2018). "C-reactive protein (CRP), an acute-phase protein secreted by the liver in response to interleukin-6 (IL-6) and tumor necrosis factor (TNF)-α, is a well-characterized marker of inflammation, and increased circulating levels have been shown to be associated with obesity and increased metabolic risk." (PMID 29760934, 2018). "Furthermore, our study mainly used obese subjects and thus the association between elevated CRP levels and CVD might be, at least in part, due to obesity." (PMID 30647800, 2018). "The unreported sleep disturbance group had increased odds of elevated CRP (OR=1.34, 95% CI: 1.02, 1.76) compared to those with no sleep problems, although this association was not significant after adjusting for obesity, comorbidities, cholesterol medication, and hours of sleep." (PMID 30402295, 2018). "Both CRP and leptin could play important role in the process of obesity." (PMID 28115972, 2017). "Therefore, integrated health management intervention including both dietary supplements and health managements might affect metabolic indicators directly or indirectly by CRP to control obesity." (PMID 28115972, 2017). "CRP level might be used as a promising marker to assess improvements in obesity." (PMID 28115972, 2017). "Likewise, CRP is one of the most important inflammatory markers in obesity." (PMID 27598978, 2017). "Third, our results from separately controlling for each of obesity-related factors such as BMI, WHR, and FM in regression model may not sufficient to exclude the influence of obesity on the association between OSA and elevated CRP levels." (PMID 27684378, 2016). "The finding that CRP was significantly associated with an increased risk of CVD and decreased the BMI-associated CVD risk substantially, could imply that interleukin-6-related pathways may play a role in mediating overweight- and obesity-related CVD." (PMID 26035431, 2015). "While the direct inflammatory and antioxidant mechanisms purported to influence the relationship between poor sleep quality and obesity remain unknown, our study provides initial evidence of a mediating role of CRP and vitamin C on the relationship between sleep quality and abdominal obesity." (PMID 26568665, 2015). "The inflammatory marker CRP may have a role to play in the preoperative routine forgrade II or III obesity patients who are candidates for bariatric surgery, as a markerfor the risk of immediate postoperative complications or be used to make up part of thescore for stratification of surgical risk." (PMID 26537265, 2015).
Obesity (continued). "It is now generally accepted that obesity represents a low-grade chronic inflammatory state, characterized by abnormal profile of cytokine secretion, increased synthesis of acute-phase reactants, such as C-reactive protein (CRP), and the activation of proinflammatory signaling pathways." (PMID 25684862, 2015). "As obesity-related proinflammatory response is associated with higher plasma leptin levels, we also assessed whether LEP DNA methylation levels in blood cells are associated with circulating levels of the pro-inflammatory CRP." (PMID 25929254, 2015). "Also the results of this study showed that the obesity and metabolic alterations rather than CRP, are associated with the PCOS." (PMID 25904961, 2015). "Our data indirectly suggests that interleukin-6 originating from fat tissue may play a role in overweight- and obesity-related CVD, because CRP decreased the BMI-associated CVD risk markedly, and because it is well known that CRP itself is only a marker not a cause of CVD." (PMID 26035431, 2015). "IL-6 signaling pathways are involved in the liver synthesis of C-reactive protein (CRP), and CRP is elevated in children with sleep-disordered breathing, whereby both IL-6 and CRP levels correlate with degree of hypoxemia and sleep disruption, independently of the degree of obesity." (PMID 24991089, 2014). "Since decreased plasma levels of total LPC and LPC species may be due to obesity and the inflammatory status in these subjects, respectively, we correlated BMI and CRP as an indicator of inflammation with total LPC as well as with different LPC species within the group of obese subjects." (PMID 25340546, 2014). "In recent years, it has been demonstrated that obesity is associated with low-grade inflammatory process characterized by the increase in circulating levels of pro-inflammatory cytokines such as IL-6, TNF-alpha, and acute-phase proteins (CRP and haptoglobin) in healthy obese subjects." (PMID 23690772, 2013). "Elevated CRP was found to be significantly more frequent in patients with recurrent depressive disorders (RDD) (35.5%; χ2 test, P = 0.001, Cramer V = 0.29) than in controls (12.5%) and was associated with lowered high-density lipoprotein and overweight/obesity." (PMID 24170724, 2013). "There is some debate on whether CRP levels are dependent on obesity or the severity of OSA." (PMID 23518041, 2013). "Thus, an independent inverse correlation between plasma adiponectin levels and hs-CRP may suggest that decrease of adiponectin contributes to the systemic and vascular inflammation commonly found in obesity." (PMID 23843680, 2013). "Obesity is associated with low-grade chronic inflammation and adipose tissue is a main source of excess production of cytokines like tumour necrosis factor-α (TNF-α), interleukin-18 (IL-18), IL-1, IL-8, monocyte chemoattractant protein-1, and C reactive protein (CRP)." (PMID 23431426, 2013). "In addition, increases in serum inflammatory markers such as interleukin-6 (IL-6) and C-reactive protein (CRP) have been shown to exacerbate cognitive decline in older adults with metabolic syndrome, a condition defined by cooccurring obesity, hypertension, dyslipidemia, and hyperglycemia." (PMID 22461977, 2012). "Our research was conducted to evaluate the association between genotype and haplotype frequencies of SNPs rs1130864, rs1205, rs2794521, and rs3093062 in the CRP gene with serum levels of CRP, in healthy, obese, T2D obese, and T2D without obesity, or with the risk score of CHD." (PMID 23049543, 2012). "Thus, we tested the hypothesis that the obesity-related low-grade chronic inflammation, evaluated by spleen volume and C-reactive protein (CRP), could affect the IGF-I axis status in overweight/obese, independently of HS." (PMID 21846339, 2011).